SNHG12 (small nucleolar RNA host gene 12)
Synonyms: C1orf79; PNAS-123; LINC00100; ASLNC04080; LINC001000; NCRNA00100
Gene: Long non-coding RNA gene on chromosome 1 (28,578,536 to 28,583,132, reverse strand). Ensembl gene ENSG00000197989.
Gene Ontology:
Biological process: RNA processing
Cellular component: nucleolus
Diseases named in the same sentence as SNHG12 in open-access papers:
SNHG12 is named in the same sentence as 72 diseases in open-access papers, as found by Europe PMC text mining. Sharing a sentence is not in itself a finding about the gene and the disease. The quoted sentences say what the papers report.
osteosarcoma (24 papers, 2016 to 2024). A usually aggressive malignant bone-forming mesenchymal neoplasm, predominantly affecting adolescents and young adults. "SNHG12 has been implicated in various cancers, such as gastric cancer, triple-negative breast cancer, glioma, and osteosarcoma." (PMID 36386805, 2022). "In osteosarcoma, SNHG12 causes increased cell proliferation and migration as well as stimulated angiogenesis, through up-regulation of AMOT (angiomotin)." (PMID 32318335, 2020). "Studies have implicated SNHG12 in a number of cancers, such as breast, gastric, osteosarcoma, and glioma and other cancer types detailed in this review." (PMID 31620362, 2019). "SNHG12 stimulates the Notch signaling pathway and precipitates enhanced oncogenesis and osteosarcoma dissemination by sponging miR-195-5p." (PMID 39015175, 2024). "For example, SNHG12 is significantly upregulated in osteosarcoma tissues and cell lines, and osteosarcoma patients with high levels of SNHG12 tend to have a poor prognosis." (PMID 37278038, 2023). "Osteosarcoma tissues exhibit overexpression of SNHG12, which then leads to an increase in the tumorigenesis and metastasis induced by Notch2-and insulin-like growth factor 1 receptor (IGF1R) through the regulation of miR-195-5p." (PMID 38028627, 2023). "Knockdown of SNHG12 suppressed metastasis, epithelial‐mesenchymal transition, and mediated doxorubicin resistance of osteosarcoma." (PMID 35726651, 2023). "In vitro studies also showed the effect of SNHG12 repression in inhibiting proliferation, migration and invasion, and metastasis in osteosarcomas and gastric cancer." (PMID 35406435, 2022). "SNHG12 mediated doxorubicin resistance in osteosarcoma, while its knockdown contributed to the upregulation of miR-320a and improved the sensitivity to this drug." (PMID 35406435, 2022). "Experimental analysis showed that SNHG12 is an endogenous sponge for microRNAs in cervical, prostate, gastric, breast, lung, colorectal cancer, gliomas, osteosarcoma, hepatocellular, papillary thyroid, and clear cell renal cell carcinomas." (PMID 35406435, 2022). "Recent research has demonstrated that SNHG12 was significantly overexpressed in osteosarcoma, and high expression of SNHG12 tended to lead to a poor prognosis of osteosarcoma patients." (PMID 33653335, 2021). "SNHG12, the only lncRNA in this module, promotes tumorigenesis and metastasis in human osteosarcoma cells and hepatocellular carcinoma." (PMID 32943987, 2020). "SNHG12 was first characterized over-expressing in osteosarcoma cells, which promoted cell proliferation and migration by up-regulating angiomotin gene expression." (PMID 31114448, 2019). "The microRNA sponging function of SNHG12 also has been disclosed in osteosarcoma, wherein promoted tumorigenesis and metastasis by up-regulating Notch2 via competing with miR-195-5p." (PMID 31114448, 2019). "Small nucleolar RNA host gene 12 (SNHG12) has been increasingly recognized involving in variety of human cancers such as human osteosarcoma cell, nasopharyngeal carcinoma cell, and human endometrial carcinoma." (PMID 31114448, 2019). "Long non-coding RNA small nucleolar RNA host gene 12 (SNHG12) was a novel lncRNA identified to be up-regulated in several cancer cells, such as human osteosarcoma cell, nasopharyngeal carcinoma cell, and human endometrial carcinoma." (PMID 28225893, 2017). "They found that SNHG12 mRNA expression was upregulated in osteosarcoma tissues and cell lines compared with normal tissues and cells and that SNHG12 knockdown suppressed cell proliferation and migration but did not affect cell apoptosis." (PMID 27685633, 2016). "The amplification of the expression of the angiomotin (AMOT) gene in cells from human osteosarcomas by SNHG12 also has been reported to accelerate cellular replication and migration, while the knockdown of SNHG12 had the opposite consequence but failed to influence programmed cell death." (PMID 39015175, 2024).
osteosarcoma (continued). "Moreover, the increased expression of SNHG12 promoted the development of doxorubicin resistance through the SNHG12/miR-320a/MCL1 axis in osteosarcoma cells." (PMID 35592674, 2022). "Additionally, OIP5-AS1 and SNHG12 were involved in osteosarcoma doxorubicin resistance via miR-200b-3p/FN1 and miR-320a/MCL1 pathways, respectively." (PMID 33639865, 2021). "For example, SNHG12 could facilitate the proliferation and migration of human osteosarcoma cells by up-regulating angiomotin gene expression." (PMID 33009370, 2020). "SNHG12 is higher in Dox-resistant osteosarcoma cells than in sensitive cells and correlates with lower patients’ survival: specifically, SNHG12 induces resistance by up-regulating the mir320a/myeloid cell leukemia 1 (MCL1) axis that protects from the apoptosis induced by Dox." (PMID 32599901, 2020). "Recent studies have showed that SNHG12 can regulates the Wnt/β-catenin signaling pathway in papillary thyroid carcinoma cells to promote cellular proliferation and metastasis, but also plays a regulate the occurrence and development of glioma, osteosarcoma and gastric carcinoma." (PMID 36105104, 2022). "In addition, SNHG12 expression in different osteosarcoma cell lines was found to be up-regulated by ~6.2-fold in 143B cells, up to ~3.9-fold in MG63 cells, ~5.4-fold in MG63/DXR cells, and up to ~5.6-fold in U2OS cells compared to normal human osteoblast cell lines." (PMID 31620362, 2019). "For example, SNHG12 participates in regulating IGF1R-induced proliferation and metastasis of osteosarcoma cells by modulating miR-195-5p; BANCR regulates Wnt/β-Catenin signaling pathway by sponging miR-195-5p, thereupon promoting pancreatic cancer progression." (PMID 35037833, 2022). "A recent study demonstrated that the lncRNA small nucleolar RNA host gene 12 (SNHG12) promotes cell proliferation and migration by upregulating AMOT gene expression in human osteosarcoma." (PMID 28073380, 2017). "Osteosarcoma patients with higher SNHG12 expression were more inclined to develop advanced Enneking stage, and vascular invasion occurred more in HCC patients with higher SNHG12 expression." (PMID 33124951, 2020). "Moreover, increased SNHG12 transcript levels have been noted in cells from osteosarcomas that demonstrated DXR resistance, as opposed to those that are susceptible to this drug at cytotoxic levels." (PMID 39015175, 2024).
gastric cancer (19 papers, 2019 to 2024). A primary or metastatic malignant neoplasm involving the stomach. "For instance, lncRNA H19, HOXA11-AS, and SNHG12 were all associated with gastric cancer progression." (PMID 34660323, 2021). "With regard to ceRNA, SNHG12 has been revealed to bind to HuR protein to accelerate gastric cancer progression." (PMID 38946724, 2024). "SNHG12 is highly expressed in gastric carcinoma, non‐small cell lung cancer, and liver carcinoma, and is involved in tumor development and drug resistance, which is an underlying therapeutic target and biomarker for human cancers." (PMID 38946724, 2024). "LncRNA small nucleolar RNA host gene 12 (SNHG12) has been studied in-depth in many pathological processes, including glioblastoma, cervical cancer, pancreatic cancer, renal cell carcinoma, and gastric cancer." (PMID 35624111, 2022). "Among them, SNHG12 has been reported in highly expressed quantities in gastric cancer, triple-negative breast cancer and colon cancer with direct proportion to the growth and development of tumor tissue and cells." (PMID 32432698, 2020). "SNHG12 activation of PI3K/AKT signaling pathway in gastric cancer promoted cell proliferation, cell cycle progression, and inhibition of apoptosis." (PMID 32318335, 2020). "It was reported that SNHG12 accelerated the progression of gastric carcinoma by regulating Argo2 expression via sponging miR-199a/b-5p." (PMID 33294456, 2020). "We compared the long non-coding RNA levels in gastric cancer (GC) and para-cancerous tissues in the Gene Expression Omnibus, and found that small nucleolar RNA host gene 12 (SNHG12) was upregulated in GC tissues." (PMID 31808752, 2019). "In addition, the expression level of SNHG12 in gastric cancer, osteoma, colon cancer, hepatocellular carcinoma, and various other tumors is related to the clinical features and prognosis of cancer patients." (PMID 34372942, 2021). "Moreover, a single study reported that gastric cancer patients with upregulated SNHG12 expression had a worse DFS after surgery." (PMID 33124951, 2020). "Moreover, SNHG12 could promote the proliferation of gastric carcinoma cells BGC-823 by targeting miRNA-199a/b-5p." (PMID 35704638, 2022). "Thus, in accordance with its tumorigenic role in other cancers, SNHG12 may be a promising biomarker for gastric cancer." (PMID 31808752, 2019). "This is consistent with the result that under the condition of SNHG12 addition, gastric cancer cell proliferation, migration and invasion were notably heightened and cell apoptosis was lessened to accelerate the malignant progression of GC by activating the phosphatidylinositol 3-kinase/AKT pathway." (PMID 34332535, 2021). "Previous studies have shown SNHG12 plays an important role in the development of triple-negative breast cancer, prostate cancer, colon cancer, gastric cancer and gliomas." (PMID 32432698, 2020). "However, the role of SNHG12 in the metastasis of gastric cancer (GC) has not yet been thoroughly investigated." (PMID 33994849, 2021).
hepatocellular carcinoma (18 papers, 2017 to 2025). A malignant tumor that arises from hepatocytes. "For instance, SNHG12 targets miR‐199a‐5p within hepatocellular carcinoma through a ceRNA mechanism, thereby regulating the MLK3/IkB‐α/NF‐kB signaling." (PMID 38946724, 2024). "In hepatocellular carcinoma, SNHG12 induces miR-199a/b-5p underexpression, which leads to the overexpression of MLK3 (mixed-lineage kinase 3) and the stimulation of the NF-κB pathway." (PMID 32318335, 2020). "Previous studies have indicated that SNHG12 promotes the tumorigenesis of multiple cancers, including hepatocellular carcinoma, glioma and breast cancer." (PMID 31808752, 2019). "In hepatocellular carcinoma, SNHG12 promoted tumorigenesis and metastasis by acting as an endogenous miR-199a/b-5p sponge to regulate the expression of MLK3 and affect the NF-κB pathway." (PMID 29137407, 2017). "Furthermore, Snhg12 promotes tumourigenesis and metastasis in hepatocellular carcinoma, and vascular smooth muscle cell proliferation and migration via targeting miR-199a-5p." (PMID 40503725, 2025). "Several data showed that SNHG12 functions as a competing endogenous RNA [ceRNA] for some miRNAs, such as miR-119a/b-5p in hepatocellular carcinoma and miR-181a in non-small cell lung cancer, highlighting the interaction between the two families of non-coding RNA." (PMID 35327332, 2022). "Similarly, a previous study also revealed SNHG12 de-suppress mixed-lineage protein kinase 3 (MLK3) by sponging miR-199a/b-5p in hepatocellular carcinoma." (PMID 29137407, 2017). "In hepatocellular carcinoma (HCC), SNHG12 interacts with miR‐199a‐5p and consequently up‐regulates the expression of mitogen‐activated protein kinase 3 (MLK3) as well as the phosphorylation of IkB‐α and NF‐kB." (PMID 33787057, 2021). "Recent studies show that the lncRNA small nucleolar RNA host gene 12 (SNHG12) facilitates tumorigenesis and metastasis by sponging miR-199a/b in hepatocellular carcinoma." (PMID 29282102, 2017). "Dysregulation of the lncRNA Snhg12 is involved in a variety of pathogeneses, such as those of LDL-induced endothelial cell injury in atherosclerosis and endometrial, gastric, and hepatocellular cancer." (PMID 36313450, 2022). "In addition, SNHG12 knockdown in hepatocellular carcinoma did not statistically significantly affect the expression of its snoRNAs (SNORA44, SNORA61, SNORA16A, and SNORD99]." (PMID 32318335, 2020).
renal cell carcinoma (17 papers, 2019 to 2025). "In renal cell carcinomas, SNHG12 was involved in the regulation of the CDCA3 (cell division cycle associated 3) gene mediated by SP1, promoting resistance to sunitinib." (PMID 35406435, 2022). "In some specific tumors, the oncogenic roles of SNHG12 were also reported in vitro and in vivo experiments, such as renal cell carcinoma and cervical cancer." (PMID 34239888, 2021). "In renal cell carcinoma, SNHG12 promotes proliferation, migration, invasion and sunitinib resistance via the SNHG12/SP1/CDCA3 axis." (PMID 34195070, 2021). "Corresponding to these results, further analysis revealed that SNHG12 promoted renal cell carcinoma by modulating HIF1α expression via the sponging of miR-199a-5p." (PMID 31620362, 2019). "Very recently it was demonstrated that SNHG12 was aberrantly up-regulated (~1.75-fold) in renal cell carcinoma cells compared to control samples." (PMID 31620362, 2019). "Interestingly, SNHG12 has been reported to accelerate the progression of renal cell cancer, and high expression of SNHG12 positively correlates with poor clinical outcome of patients with ccRCC." (PMID 33787057, 2021). "For instance, SNHG12 upregulation increased the expression of hypoxia-inducible factor 1 α (HIF1α) by targeting miR-199a-5p, which induced cell proliferation, migration, and invasion in renal cell carcinoma." (PMID 33124951, 2020). "However, the expression status and involvement of SNHG12 in renal cell carcinoma is still elusive." (PMID 31114448, 2019). "SNHG12 promoted tumor progression and sunitinib resistance by upregulating CDCA3 in renal cell carcinoma." (PMID 35721492, 2022). "SNHG12, also known by other names (LNC04080, ASLNC04080, C1orf79, LINC00100, PNAS-1230), was overexpressed in several cancers, including non-small-cell lung cancer, renal cell carcinoma, and prostate cancer, and its levels correlated with tumor size, progression, and metastasis." (PMID 38279317, 2024). "MiR-200c-5p inhibition could reduce the effects of SnHG12 downregulation on cell viability and apoptosis, without affecting SnHG12 expression levels in renal cell carcinoma." (PMID 34409072, 2021).
glioma (16 papers, 2019 to 2025). A benign or malignant brain and spinal cord tumor that arises from glial cells (astrocytes, oligodendrocytes, ependymal cells). "High expression of SNHG12 in these tumors (glioma, ACC, LAML, LIHC, MESO) was associated with poor prognosis." (PMID 34372942, 2021). "SNHG12 was upregulated in glioma and its expression was positively correlated with the glioma grades." (PMID 37047365, 2023). "In gliomas, hypomethylation of the promoter region of SNHG12 was correlated with the transcription factor SP1, leading to its up-regulation in temozolomide-resistant cell lines." (PMID 35406435, 2022). "A study reported that the hypomethylation of the promoter region of lncRNA SNHG12 led to the upregulation of SNHG12 expression in gliomas, which led to the malignant progression of gliomas." (PMID 33828990, 2021). "In the tumor samples of the TCGA database, the SNHG12 expression level was low in glioma, BRCA, LAML, LUAD, LUSC, and KICH and high in DLBG, HNSC, KIRC, and THYM." (PMID 34372942, 2021). "Taken together, these results indicate that the ceRNA network in which SNHG12 participates plays an important role in the mechanism of acquired TMZ resistance in glioma." (PMID 32039732, 2020). "Secondly, analysis of recurrent glioma tissue demonstrated increased SNHG12 expression compared to primary, treatment naive tumors." (PMID 32039732, 2020). "MiR-101-3p and miR-195 were found to be putative targets of SNHG12, which inhibited the progression of glioma by down-regulating their target genes, Forkhead Box Protein P1 (FOXP1), and Sry-Box 5 (SOX5)." (PMID 31620362, 2019). "The expression of SNHG12 was examined by three different research groups in 33, 39, and 79 glioma tissue samples compared to adjacent normal tissues and were found to be up-regulated by ~3.3, ~5.5, and ~2.2-fold, respectively." (PMID 31620362, 2019). "Knockdown of SNHG12 in the U87 and U251 glioma cells resulted in decreased cell numbers, impaired proliferation, migration, and invasion, but increased the apoptotic rate in these cells compared to control human astrocytes." (PMID 31620362, 2019). "In three independent studies SNHG12 was found to be over-expressed by ~5.2, ~3.8, and ~11-fold in the U87 glioma cell line, and ~5.3, ~4.2, and ~13-fold in the U251 glioma cell line." (PMID 31620362, 2019). "In the TDP43/SNHG12/miR-195/SOX5 pathway of glioma cells, SOX5 promotes the transcription of SNHG12 and forms a positive feedback loop to regulate the biological behavior of glioma cells." (PMID 30736838, 2019). "In addition, they showed that tumor suppressor miR-195, downregulated in gliomas, targeted SNHG12 in a sequence-specific manner and suggested the reciprocal repression feedback loop between SNHG12 and miR-195." (PMID 37047365, 2023). "Taken together, these findings suggest that SNHG12 acts as a key player in the progression of glioma by its involvement in the miR-101-3p/FOXP1 axis, and the miR-195/SOX5 axis, which are stabilized by the binding of the RNA-binding proteins, HuR and TDP43, respectively." (PMID 31620362, 2019). "In addition, SOX5 was found to regulate the malignant progression of glioma cells via direct binding to the promoter of its downstream target gene Gelsolin, and the promoter of SNHG12." (PMID 31620362, 2019). "However, the expression levels of Neat1, Mir142hg, Pvt1, Mir17hg, SNHG12 and Meg3 showed opposite trends, which may correlate with the distinct inflammatory profiles and immunophenotypes of the different glioma models analyzed." (PMID 40527978, 2025). "Thus, SNHG12 may serve as a potential biomarker/target for glioma." (PMID 31620362, 2019). "The pooled results also showed that patients with higher SNHG12 expression level were more exposed to worse clinicopathological outcomes including larger tumor size, higher Gleason score in prostate cancer, advanced TNM stage, higher WHO grade in glioma, LNM, and DM." (PMID 33124951, 2020).
glioma (continued). "Similarly, SNHG12 could upregulate SOX5 expression and exert oncogenic functions in glioma cells, while SOX5 increases SNHG12 expression by activating its promoter." (PMID 31186064, 2019).